Y_RNA (Y RNA )
Gene: Miscellaneous RNA gene on chromosome 1 (247,997,000 to 247,997,096, forward strand). Ensembl gene ENSG00000199442.
Homologues: Orthologues: chimpanzee Y_RNA (99% identical), macaque Y_RNA (93% identical). Paralogues in human: Y_RNA (91% identical), Y_RNA (90% identical), RNY3 (88% identical), RNY3P1 (88% identical), Y_RNA (88% identical), Y_RNA (87% identical), Y_RNA (86% identical), RNY3P2 (85% identical), Y_RNA (85% identical), Y_RNA (84% identical), RNY3P14 (82% identical), Y_RNA (82% identical), and 94 more.